CD226 (CD226 molecule)
Diseases named in the same sentence as CD226 in open-access papers (continued):
Sharing a sentence is not in itself a finding about the gene and the disease.
tumor (continued). "Third, the TIGIT on the surface of tumor-infiltrating CD8+T cells competitively binds to the PVR on the surface of tumor cells or dendritic cells, resulting in the failure of T cell-activated receptor CD226 to bind to PVR, thus inhibiting the activity of T cells." (PMID 37035135, 2023). "Based on these findings, it is possible to hypothesize that PARPi further potentiate Th1 responses by increasing the engagement of CD226 through an increased expression of its ligand CD155 on tumor cells." (PMID 36428727, 2022). "Overall, the results from our current NK cell study suggest that CD226 signaling may also play a role in regulating the metabolism of NK or even CD8 T cells in other contexts such as infection or tumor settings." (PMID 36361628, 2022). "Furthermore, unlike CD226, CD96 was dispensable for killing of CD155-expressing tumor cells, suggesting that the stimulatory effect of CD226 is dominant." (PMID 35998045, 2022). "Indeed, tumor-infiltration by CD8+ T cells with poor CD226 expression and high levels of the other specific ligand of CD155 (T cell immunoreceptor with Ig and ITIM domains, TIGIT), is associated with T cell exhaustion and tumor progression." (PMID 36428727, 2022). "Of note, CD226 expression can be modulated also by selected anti-tumor treatments." (PMID 36428727, 2022). "Notably, the sole depletion of NK cells or CD8 T cells resulted in a CD226 dependent faster tumor progression in the VK*MYC MM model showing an ongoing attempt of immune control even under tumor progression." (PMID 34584204, 2022). "In view of the expression of CD137 ligand (CD137L) by dendritic cells and by numerous tumor lines, CD137 may down-modulate CD226 both in early phases of anti-tumor immune responses and in later phases at the tumor site, respectively." (PMID 35874734, 2022). "The co-stimulatory CD226 signaling contributes to NK cell function and tumor clearance." (PMID 36361628, 2022). "CD226 has been involved in anti-tumor NK cell and T cell-mediated cytotoxicity by contributing to the establishment of a strong interaction with tumor cells through the engagement of CD155 that is required for an effective killing of tumor cells and inhibition of their metastatic spreading." (PMID 36428727, 2022). "In this context, it is important to again emphasize that PVR is widely expressed, even by most tumor cells, suggesting that CD226 activation may participate in the T cell effector activity more so than CD28, whose activating ligand is limited to immune cells." (PMID 35263569, 2022). "TIGIT competes with CD226 to bind to PVR (CD155) and Nectin-2 (CD112) two molecules often up-regulated on tumor cells thus playing an important role in the NK-cell activity inhibition in part counterbalanced by the co-stimulatory activity exert by DNAM-1(CD226) receptor." (PMID 36291830, 2022). "CD226 downregulation could be a barrier to the effective targeting of this axis because it is required for enhancing the anti-tumor CD8+ T cell responses upon PD-1 and TIGIT blockade." (PMID 36544779, 2022). "Thus, full restoration of CD226 signaling, and optimal anti-tumor CD8+ T cell responses, requires blockade of TIGIT and PD-1, providing a mechanistic rationale for combinatorial targeting in the clinic." (PMID 35263569, 2022). "In fact, blocking PD-1 and inhibiting CD226 function compromise tumor clearance by CD8 T cells." (PMID 36361628, 2022). "The anti-tumor effect of blocking TIGIT may also need to consider the activation status of the CD226." (PMID 35433470, 2022). "Moreover, in Treg-mediated tumor immune escape, Tregs express relatively high levels of TIGIT and low levels of CD226 compared with effector T cells (Teffs), resulting in a high ratio of TIGIT/CD226 expression and accelerating tumor development." (PMID 33549054, 2021).
tumor (continued). "Similarly to the CTLA-4/CD28 dynamic, TIGIT outcompete DNAM-1 (CD226) and CD96 for the binding of CD155, impeding DNAM-1 positive co-stimulation and delivering a direct inhibitory signal as shown in TIGIT-deficient mice with delayed tumor growth." (PMID 34572799, 2021). "On the other hand, the CD226 gene encodes the glycoprotein CD226, also known as DNAM-1 (DNAX Accessory Molecule-1), which is expressed on the surface of natural killer (NK) cells and is involved in T cell-mediated cytotoxicity against certain tumours." (PMID 33921837, 2021). "Moreover, inhibition of miR-150 improved tumor surveillance by reversing CD226 expression and subsequently reinstating cytotoxic NK cell activity in an animal model." (PMID 34944871, 2021). "In Bcl9-depleted MC38 tumors, CD226+CD8+ T cell tumor infiltration was also increased." (PMID 34417435, 2021). "Given the importance of CD226 in the lysis of tumor cells, combinational therapies based on the blockade of inhibitory receptors in this family could be very attractive." (PMID 34174928, 2021). "NK3.3-derived EVs also contained cytotoxic proteins required for NK anti-tumor activity: NKLAM, perforin, granzymes A and B, and granulysin, as well as immune-associated proteins MHC I and II and DNAX Accessory Molecule (DNAM-1; CD226), an activating receptor on NK cells." (PMID 34368150, 2021). "Notably, CD155 on tumor cells was reported to drive resistance to immunotherapy by inducing the degradation of CD226 in CD8+ T cells." (PMID 34150627, 2021). "CD226 has been reported to be involved in anti-tumor response by regulating NK cells." (PMID 33469055, 2021). "CD8+ T cells or DX5+ (CD49b) NK cells isolated from CD226-deficient mice are less cytotoxic to PVR-expressing tumor cells but not to PVR-negative tumor cells." (PMID 33670993, 2021). "Studies have shown that CD226 plays an important role in the killing of tumor cells by NK cells." (PMID 32850777, 2020). "Moreover, the decrease of CD226+ NK cells percentage correlated with the tumor histological grade and lymph node metastatic spreading." (PMID 33321719, 2020). "In recent years, some researches began to pay attention to the expression of CD226 in tumor cells." (PMID 32850777, 2020). "For example, low-dose chemotherapeutic agents, including oxaliplatin, are capable of upregulating ligands for the activating receptors NKG2D and DNAX accessory molecule-1 (DNAM-1; CD226) and TRAIL in multiple tumor lines leading to enhanced susceptibility to NK cell cytotoxicity." (PMID 32153361, 2020). "The function of CD226 in recognition of tumour cells by NK cells has been previously examined." (PMID 30908480, 2019). "Additionally, by neutralising TGFβ in the platelet releasate (from platelet cloaked tumour cells) using anti-TGFβ antibody we observed rescue of CD226 suppression, supporting TGFβ dependant regulation of this receptor." (PMID 30908480, 2019). "In this regard, among the activating receptors expressed by NK cells, NKG2D, DNAM-1 (CD226) and NKp30 are emerging as key receptors for the recognition of MM cells, being engaged by their ligands expressed by tumor cells and thus triggering NK cell cytotoxicity." (PMID 30501078, 2018). "On the one hand, IL-2-stimulated CD226−/− NK cells could perform missing self-reactions against tumour cells in vitro, while on the other hand CD226−/− mice exhibited slightly reduced capacity for missing self rejection of MHC-I− cells in vivo." (PMID 28561023, 2017). "However, the possible role of Fhit, CD226, and Emp1 as tumor suppressors in CD8+ Dnmt3aΔ/Δ PTCL is unclear." (PMID 27690235, 2016). "In contrast, we detected only three genes—CD226, Fhit, and Emp1—whose hypermethylation correlated with underexpression, suggesting that most of the cancer-specific hypermethylation has little effect on gene expression and tumor progression." (PMID 27690235, 2016). "Recently, more attention has been paid to a putative role for CD226 in tumor development." (PMID 19490613, 2009).
tumor (continued). "Just as tumor cells evade recognition by other costimulatory molecules, leading to reduced T-cell antigen sensitivity, naïve T cells may require additional costimulation by CD226 to increase their sensitivity to antigen recognition." (PMID 39349829, 2024). "In addition, the growth of implanted MC38-OVA tumor cells was not controlled in CD226-deficient mice." (PMID 39349829, 2024). "The association between the percentages of CD226+CD8+IFN-γ+T cells/CD8+CD226+T cells, CD226+CD8+IFN-γ+T cells/CD8+CD226+T cells in the epithelial cell region, and CD226+CD8+IFN-γ+T cells/CD8+CD226+T cells in the stromal cell region in tumor and clinical features of GC patients." (PMID 37056782, 2023). "Intracellularly, activated CD226 aggregates lymphocyte function-associated antigen 1 (LFA-1) to conformationally change intracellular adhesion molecule 1 (ICAM-1), which recruits Fyn and then drives activation of the Akt signaling pathway to promote NK/T cell-mediated tumor cytotoxicity." (PMID 37291608, 2023). "As CD28 and CD226 provide two important co-stimulatory pathways, loss of both may mark cells no longer capable of exerting anti-tumor effector function." (PMID 35263569, 2022). "Similarly, our analysis revealed significantly reduced expression of NCRs like CD335/NKp46 and activating co-receptors such as CD226/DNAM-1 on tumor-derived CD158ab+ NK-cells accompanied by a restricted capacity to produce IFN-γ or perforin after stimulation with PMA/Ionomycin." (PMID 35474089, 2022). "Notably, tumour CD155 (the binding partner for TIGIT) expression has been linked with resistance to αPD-1 therapy in patients with metastatic melanoma, while expression of CD155 on cancer cells ablates CTL activation via CD226 degradation." (PMID 33401460, 2021). "Upregulation of CD226 is found in peripheral blood CD8+T cells from PDAC patients after mFOLFIRINOX chemotherapy, which is associated with an elevated responsiveness of antigen-specific CD8+T cells to treatment with anti-TIGIT or anti-PD-1 mAbs, and has also been reported in the mouse tumor models." (PMID 33670993, 2021). "Moreover, the reduction of CD226+ and CD96+ NK cells is correlate with tumor histological grade and lymph node metastasis, and the decreased percentages of CD226+ and CD96+ NK cells could cause tumor immune escape in PC patients." (PMID 33128857, 2020). "These include NKG2D, FCγIII (CD16), FasL, TRAIL and DNAM‐1 (CD226).61, 62, 63, 64, 65 Vγ9+Vδ2+ T cells recognise tumor‐derived phosphorylated prenyl metabolites in a TCR‐dependent manner, which may accumulate intracellularly as a by‐product of dysregulated tumor metabolism." (PMID 31624593, 2019). "Moreover, the abnormal expression of CD226 and its ligands in some tumors may be involved in the mechanisms of tumor escape, invasion, and migration." (PMID 19490613, 2009). "CD155 was detected on TME tumor cells (TC) and TIGIT/CD96/CD226 were detected on both TC and stromal tumor-infiltrated lymphocytes (TILs)." (PMID 41181119, 2025). "CD155 interacts with both the costimulatory receptor CD226 and the inhibitory receptor CD96, influencing immune responses ranging from enhanced NK cell adhesion and cytotoxicity to tumor immune evasion and metastasis." (PMID 40362354, 2025). "For instance, the co-immunostimulatory genes CD226 and CD28 are essential for T cell activation and enhancement of anti-tumor immune responses." (PMID 40723280, 2025). "TIGIT (T cell immunoreceptor with Ig and ITIM domains) competes with the co-stimulatory receptor CD226 for binding to CD155, which is expressed in tumor cells and antigen-presenting cells." (PMID 39857682, 2025). "CD96 belongs to the immunoglobulin superfamily and acts as a co-inhibitory receptor that competes with the co-stimulatory receptor CD226 for the shared ligands CD155 (PVR) and CD211 (NECTIN1), both of which are expressed on tumor and myeloid cells." (PMID 39811671, 2025).
tumor (continued). "By inhibiting CD226 signaling, TIGIT suppresses T cell and natural killer (NK) cell functions, contributing to the tumor’s immune evasion." (PMID 39857682, 2025). "CD226highCD8+ T cells exhibit greater responsiveness and self-renewal at tumor sites, and anti-TIGIT treatment enhances their function by promoting CD226 phosphorylation." (PMID 40723878, 2025). "It competes with the co-stimulatory receptor CD226 (DNAM-1) for binding to shared ligands CD155 (PVR) and CD112 (PVRL2) on antigen-presenting cells and tumor cells." (PMID 40777027, 2025). "TIGIT, CD226, CD96 and PVRIG are expressed on T and NK cells, whereas CD155 (PVR) is often overexpressed on tumour cells." (PMID 41462864, 2025). "In patients with early-stage NSCLC, tumor-infiltrating NK cells demonstrate diminished expression of activating receptors (NKp30, NKp80, CD16, and CD226) alongside reduced degranulation capacity and cytokine production." (PMID 41254082, 2025). "The binding of CD226 to its ligand CD155 promotes an antitumour immunity response, while TIGIT competitively interacts with CD155 to induce tumour-immune invasion." (PMID 41462864, 2025). "In PanC patients, the percentage of the activating KIR receptors (DNAM1—CD226) and CD96 on NK cells is low, and reduced expression of these molecules correlates with the tumor histological grade and lymph node metastasis." (PMID 40136652, 2025). "Recognition of tumor antigens for cytotoxicity: Other receptors such as NKG2D, NKp30, NKp44, and DNAM-1 (CD226), similar to natural killer (NK) cells, facilitate the recognition and elimination of tumor cells." (PMID 40558272, 2025). "Recent studies of tumor-infiltrating T cells showed that the success of PD1 or TIGIT inhibition as immunotherapy depends on the presence of CD226 and TIGIT co-expressing T cells in the tumor." (PMID 38533515, 2024). "In PM1, CD226 was expressed in CD27+ CD4+ and CD4+ Memory subpopulations, and corresponding ligands in tumor cells were TIGB2, NECTIN2 and PVR." (PMID 38528036, 2024). "C1Qhigh TAMs interact principally with aDTCs via the epiregulin-epidermal growth factor receptor (EGFR) and CD226-NECTIN2 receptor–ligand pairs, which are involved in tumor-cell survival and proliferation." (PMID 38460015, 2024). "In this review, we focus on the roles of CD226 and CD2 in modulating the responses of T cells, especially within the context of tumor immunity." (PMID 39349829, 2024). "In the context of cancer, the interaction between CD226 and CD155 is crucial for activating anti-tumor immune responses." (PMID 38229100, 2024). "This review explores the roles of CD226 and CD2 in regulating T cell responses, particularly in tumor immunity." (PMID 39349829, 2024). "It was found that CD226 was downregulated in TIGIT+CD8+ follicular lymphoma T cells compared with TIGIT−CD8+ cells, which further promoted the immune escape process of tumor cells." (PMID 38229100, 2024). "Studies have shown an inverse correlation between CD226 and TIGIT or PD-1 in tumor-infiltrating CD8 + T cells (CD8+TILs)." (PMID 39349829, 2024). "Secondly, in addition to inhibiting cancer cells through single-chain antibody recognition of tumor surface antigens, NK cells can also recognize various ligands through multiple receptors such as NCRs (NKp46, NKp44, and NKp30), NKG2D, and DNAM-1 (CD226)." (PMID 38221520, 2024). "To explore the potential impact of the tumour microenvironment on immune homeostasis between TIGIT, CD96 and CD226 in LUAD, we performed correlation analyses among these three receptors." (PMID 38279870, 2024). "TIGIT and CD226 can compete for binding with CD155, and induce different immune responses in the tumor environment." (PMID 39113892, 2024). "We then investigated the effects of ADCC mediated by DB against GD2-positive NB cells on the expression of CD226, TIGIT and PD-1 by NK cells, and on the expression of CD112, CD155 and PD-L1 by tumor cells." (PMID 37444427, 2023).
tumor (continued). "In preclinical models, co-targeting PD-1 and GITR improves anti-tumor efficacy, possibly by restoring TIGIT/CD226 balance and preventing SHP2-mediated dephosphophorylation of the CD226 intracellular domain." (PMID 37335294, 2023). "Here we show, by analysing lymphocytes from matched human tumour and peripheral blood samples, that TIGIT and CD226 co-expression is rare on tumour-infiltrating lymphocytes." (PMID 37596248, 2023). "CAR-NKs potentially eliminate tumor cells via NCRs, NKG2D, DNAM-1 (CD226) and certain activating KIRs (KIR2DS1, KIR2DS4, and KIR2DL4) independent of CAR, as well as through CD16-mediated antibody-dependent cell-mediated cytotoxicity (ADCC)." (PMID 36750830, 2023). "CD226 was a receptor molecule that competing with TIGIT for the same ligands, and has been shown to enhance the cytotoxic and anti-tumor responses of mouse NK cells." (PMID 37426809, 2023). "The impact of BCL9 suppression on promoting CD155 expression by tumor cells was recently demonstrated, providing new insight into the role of BCL9 in regulating CD226 and CD96 immune receptors." (PMID 36717657, 2023). "Generally, the expression of CD226 in CD4+, CD8+T cells, or Tregs in normal tissues was higher than that in tumor tissues." (PMID 37056782, 2023). "Alongside natural cytotoxic activity against tumor cells, CAR-NK cells can also be activated through CAR-independent mechanisms, such as NCRs, NKG2D, costimulatory receptor DNAM-1 (CD226), certain activating KIRs, and through CD16-mediated ADCC." (PMID 36499331, 2022). "In particular, the anti-tumor activity of a combination of anti-PD-L1 and anti-TIGIT mAbs has been shown to be abolished by CD226 blockade." (PMID 36428727, 2022). "TIGIT shows higher affinity to CD155, which is expressed on dendritic cells and tumor cells, than the immune-activating receptor CD226 (also known as DNAM1) on the cytotoxic T cells and NK cells, resulting in suppression of immune activation." (PMID 35572593, 2022). "Tumor cells trigger several activating receptors, such as NKG2D, natural cytotoxicity receptors (NCRs), and DNAX accessory molecule-1 (DNAM-1/CD226)." (PMID 36612080, 2022). "At the cellular level, scRNA-seq and CyTOF of NSCLC patients revealed that while PD-1 and TIGIT were expressed throughout the CD8+ T cell compartment, CD226 and CD28 were co-expressed by distinct populations likely important for tumor immunity." (PMID 35263569, 2022). "Platelets reduce tumor cell recognition and cytotoxicity by NK cells by reducing the expression of CD112 and CD155 on tumor cells and their related receptors CD226 and CD96 on the NK cells." (PMID 35936717, 2022). "Co-expression of CD226/DNAM-1 and CD159c/NKG2C was significantly lowered in tumor cell suspensions as compared to peripheral blood of GBM patients or control individuals." (PMID 35474089, 2022). "Although less well studied, CD226 is a costimulatory receptor regulated by TIGIT and exhibits multifaceted functions in anti-tumor CD8+ T cell responses." (PMID 35263569, 2022). "These receptors compete with the costimulatory receptor DNAX accessory molecule 1 (DNAM1, or CD226) for binding to PVR and function over time to suppress T and NK cell functionality in the tumor microenvironment (TME)." (PMID 34150627, 2021). "Engagement of CD226 with its ligands PVRL2 and CD155 on target cells is essential for enhancing the anti-viral and anti-tumor functions of NK cells and T cells, whereas CD96, TIGIT and PVRIG counterbalance CD226-dependent lymphocyte activation." (PMID 34174928, 2021). "The best characterized activating receptors that recognize ligands expressed on tumor cells are NKG2D, CD226 (also known as DNAM-1) and NCRs, which include NKp46, NKp30 and NKp44." (PMID 33546248, 2021).